RHOA (ras homolog family member A)
Description:
Small GTPase which cycles between an active GTP-bound and an inactive GDP-bound state. Mainly associated with cytoskeleton organization, in active state binds to a variety of effector proteins to regulate cellular responses such as cytoskeletal dynamics, cell migration and cell cycle. Regulates a signal transduction pathway linking plasma membrane receptors to the assembly of focal adhesions and actin stress fibers. Involved in a microtubule-dependent signal that is required for the myosin contractile ring formation during cell cycle cytokinesis. Plays an essential role in cleavage furrow formation. Required for the apical junction formation of keratinocyte cell-cell adhesion. Essential for the SPATA13-mediated regulation of cell migration and adhesion assembly and disassembly. The MEMO1-RHOA-DIAPH1 signaling pathway plays an important role in ERBB2-dependent stabilization of microtubules at the cell cortex. It controls the localization of APC and CLASP2 to the cell membrane, via the regulation of GSK3B activity. In turn, membrane-bound APC allows the localization of the MACF1 to the cell membrane, which is required for microtubule capture and stabilization. Involved in the reorientation of endothelial cells and their actin stress fibers in response to cellular mechantransduction-mediated activation by ARHGEF40 (By similarity). Regulates KCNA2 potassium channel activity by reducing its location at the cell surface in response to CHRM1 activation; promotes KCNA2 endocytosis. Acts as an allosteric activator of guanine nucleotide exchange factor ECT2 by binding in its activated GTP-bound form to the PH domain of ECT2 which stimulates the release of PH inhibition and promotes the binding of substrate RHOA to the ECT2 catalytic center. May be an activator of PLCE1. In neurons, involved in the inhibition of the initial spine growth. Upon activation by CaMKII, modulates dendritic spine structural plasticity by relaying CaMKII transient activation to synapse-specific, long-term signaling (By similarity). Acts as a regulator of platelet alpha-granule release during activation and aggregation of platelets (By similarity). When activated by DAAM1 may signal centrosome maturation and chromosomal segregation during cell division. May also be involved in contractile ring formation during cytokinesis. (Microbial infection) Serves as a target for the yopT cysteine peptidase from Yersinia pestis, vector of the plague.
Synonyms: ARH12; ARHA; RHO12; RHOH12; EDFAOB
Tractability: Small molecule: a structure with a bound ligand is known; a high-quality ligand is known. Antibody: its Gene Ontology location is reachable by antibodies, with high confidence; UniProt places it where antibodies can reach, with medium confidence; the Human Protein Atlas places it where antibodies can reach. PROTAC: UniProt records ubiquitination sites on it; ubiquitination databases record sites on it; its protein half-life has been measured; a small molecule that binds it is known.
Target class: Enzyme; Hydrolase
Gene: Protein-coding gene on chromosome 3 (49,359,136 to 49,412,998, reverse strand). Ensembl gene ENSG00000067560.
Subcellular location: Cell membrane; Cytoplasm, cytoskeleton; Cleavage furrow; Cytoplasm, cell cortex; Midbody; Cell projection, lamellipodium; Cell projection, dendrite; Nucleus; Cytoplasm
Subcellular location (Human Protein Atlas): Cytosol; Plasma membrane
Pathways (Reactome):
Signal Transduction: Axonal growth inhibition (RHOA activation); Axonal growth stimulation; ERBB2 Regulates Cell Motility; G alpha (12/13) signalling events; G beta:gamma signalling through PI3Kgamma; PCP/CE pathway; PI3K/AKT activation; PTK6 Regulates RHO GTPases, RAS GTPase and MAP kinases; RHO GTPases Activate Formins; RHO GTPases Activate ROCKs; RHO GTPases Activate Rhotekin and Rhophilins; RHO GTPases activate CIT; RHO GTPases activate KTN1; RHO GTPases activate PKNs; RHOA GTPase cycle; RHOC GTPase cycle; TGF-beta receptor signaling in EMT (epithelial to mesenchymal transition); VEGFA-VEGFR2 Pathway
Developmental Biology: EPHA-mediated growth cone collapse; EPHB-mediated forward signaling; SLIT2:ROBO1 increases RHOA activity; Sema4D induced cell migration and growth-cone collapse; Sema4D mediated inhibition of cell attachment and migration
Hemostasis: GPVI-mediated activation cascade
Immune System: Neutrophil degranulation
Metabolism of proteins: Ovarian tumor domain proteases
Gene Ontology:
Molecular function: G protein activity; GTP binding; GTPase activity; myosin binding; protein binding; protein kinase binding
Biological process: actin cytoskeleton organization; aortic valve formation; apical junction assembly; apolipoprotein A-I-mediated signaling pathway; cell junction assembly; cell migration; cellular response to chemokine; cellular response to cytokine stimulus; cellular response to lipopolysaccharide; cleavage furrow formation; cytoplasmic microtubule organization; endothelial cell migration; endothelial tube lumen extension; establishment of epithelial cell apical/basal polarity; mitotic cleavage furrow formation; mitotic spindle assembly; negative chemotaxis; negative regulation of cell migration involved in sprouting angiogenesis; negative regulation of cell size; positive regulation of canonical NF-kappaB signal transduction; positive regulation of cytokinesis; positive regulation of leukocyte adhesion to vascular endothelial cell; positive regulation of lipase activity; positive regulation of neuron differentiation; positive regulation of protein serine/threonine kinase activity; and 31 more
Cellular component: apical junction complex; cell cortex; cell periphery; cleavage furrow; cytoplasm; cytoplasmic side of plasma membrane; cytosol; endosome; extracellular exosome; focal adhesion; glutamatergic synapse; nucleus; plasma membrane; postsynapse; vesicle; cell junction; dendritic spine; endoplasmic reticulum membrane; ficolin-1-rich granule membrane; lamellipodium; secretory granule membrane; cytoskeleton; dendrite; midbody; ruffle membrane
Genetic constraint (gnomAD): Loss-of-function variants: 3 observed, 17.89 expected, observed/expected ratio (o/e) 0.17, 90% interval 0.075 to 0.43. The upper end of that interval is the gene's LOEUF score, 0.43, which puts it in group 1 of 6, group 1 being the genes least tolerant of losing a copy. Missense variants: 56 observed, 256.05 expected, observed/expected ratio (o/e) 0.22, 90% interval 0.17 to 0.27. Synonymous variants: 98 observed, 93.52 expected, observed/expected ratio (o/e) 1.05, 90% interval 0.89 to 1.24.
Cancer hallmarks: tumour promoting inflammation (suppresses); invasion and metastasis (suppresses); invasion and metastasis (promotes); genome instability and mutations (suppresses); escaping programmed cell death (promotes or suppresses); suppression of growth (promotes)
Homologues: Orthologues: chimpanzee RHOA (100% identical), dog RHOA (100% identical), guinea pig RHOA (100% identical), macaque RHOA (100% identical), pig RHOA (100% identical), rabbit RHOA (100% identical), mouse Rhoa (99% identical), rat Rhoa (98% identical), Drosophila melanogaster Rho1 (87% identical). Paralogues in human: RHOC (92% identical), RHOB (85% identical), RAC1 (55% identical), RAC2 (53% identical), RAC3 (53% identical), RHOG (53% identical), RHOD (51% identical), RHOF (50% identical), RHOQ (50% identical), CDC42 (50% identical), RND3 (50% identical), RHOJ (48% identical), and 10 more.
Diseases named in the same sentence as RHOA in open-access papers:
RHOA is named in the same sentence as 486 diseases in open-access papers, as found by Europe PMC text mining. Sharing a sentence is not in itself a finding about the gene and the disease. The quoted sentences say what the papers report.
breast carcinoma (313 papers, 2003 to 2026). "Recent advances have also emphasized the involvement of RhoA/ROCK signaling in regulating breast cancer-associated angiogenesis and lymph angiogenesis, both of which are crucial for tumor growth and metastasis." (PMID 40388100, 2025). "RhoA has been implicated in multiple cancers including breast carcinoma, liver carcinoma, ovarian carcinoma, and gastric carcinoma." (PMID 39887960, 2025). "RHOA mutations cause a dramatic increase in breast cancer cell migration, invasion, and actin stress fiber formation, whereas Y-27632 significantly inhibited the effects of these increases." (PMID 41291745, 2025). "With regard to tumours, PHF5A is overexpressed in lung cancer, breast cancer, colorectal cancer and hepatocellular carcinoma and promotes malignant tumour biological progression associated with the NF-κB pathway, RhoA/ROCK pathway, and activation of HDAC8." (PMID 37434235, 2023). "The database for this in silico analysis revealed that SNTA1 and RhoA showed multiple deleterious mutations in breast cancers, which ultimately were shown to have a damaging impact." (PMID 35273919, 2022). "Different from the mechanism of Hhex regulation in breast cancer cells, our results showed that Hhex was associated with RHOA and CDC42 activation." (PMID 34321041, 2021). "In breast cancer cells, the loss of NaVβ4 promoted RhoA activity and the acquisition of a hybrid mesenchymal–amoeboid phenotype associated with highly invasive capacities." (PMID 34209614, 2021). "The reduced expression of RhoA increased the risk of metastasis in breast cancer, and the loss of RhoA contributed to the current of metastasis in colon cancer." (PMID 35076580, 2021). "The FAK/Src/paxillin and RhoA/ROCK1 signaling pathways were also implicated in the migration of breast cancer cells mediated by a cytoskeletal protein with a prominent GTPase activity named SEPT9 isoform 1 protein (SEPT9_i1)." (PMID 33562737, 2021). "As downstream genes of PI3K-AKT signaling, ULK1 and RHOA mutations are rarely detected in breast cancer." (PMID 34007008, 2021). "The GSEA further suggested enrichment for gene sets associated with breast cancer bone relapse and RhoA pathway in breast cancer cells with higher QPRT expression." (PMID 33613454, 2020). "Predictive diagnosis of breast cancer in predisposed individuals—both premenopausal and postmenopausal—is possible based on multiomic approach involving RhoA." (PMID 32443784, 2020). "Rac1 and RhoA are coordinated in breast cancer cell migration, so that Rac1 causes actin assembly at the leading edge of the cell migration and RhoA regulates cell contractility with more localized at the trailing edge." (PMID 33585411, 2020). "We showed that strong expression of RhoA and low expression of RhoB was associated with the basal-like subtype of breast cancer." (PMID 33162807, 2020). "CD44 has also been linked to RhoGTPase actin cytoskeletal regulators, Rac1 and RhoA, in astrocytes as well as other systems such as breast cancer cells and keratinocytes." (PMID 33020512, 2020). "The results of our in vitro invasion assays align rightly with the in vivo mouse experiments strongly suggesting the causal role of RhoA as a breast cancer metastasis suppressor." (PMID 31705019, 2019). "In our study, S1PR1 was associated with two angiogenic patterns in breast cancer by regulating the RhoA signal pathway." (PMID 30814488, 2019). "More recently, the potential role of NaVβ4 as a metastasis-suppressor gene has been described in breast cancer cells, associated with the small GTPase RhoA activity and therefore with the cytoskeleton remodeling during migration and invasiveness." (PMID 30814913, 2019). "Another recent study investigated the possibility of utilizing MMP-9 and RhoA level for breast cancer risk assessment through patient stratification." (PMID 30262739, 2018). "The loss of OBSCN caused RHOA signaling impairment leading to breast cancer initiation, progression and metastasis." (PMID 29254242, 2017).
breast carcinoma (continued). "Wnt5a promotes breast cancer cell migration via Dishevelled 2 (Dvl2)/Dishevelled-associated activator of morphogenesis 1 (Daam1)/RhoA signaling pathway." (PMID 28289332, 2017). "For example, hypoxia promotes breast cancer cell motility by inducing the expression of the genes encoding RhoA and RhoA kinase." (PMID 27590511, 2016). "The association between RHOA with breast cancer DMFS was further examined using the “Combined breast dataset” (n = 1056)." (PMID 25970788, 2015). "Recent studies have shown that miR-155 mediates TGF-β-induced EMT by targeting RhoA and induces breast cancer EMT through the loss of C/EBPβ." (PMID 25373388, 2014). "S-phage kinase-associated protein 2 (Skp2) and Myc coordinate to induced RhoA transcription and promote breast cancer metastasis." (PMID 23826080, 2013). "RhoA and RhoC GTPases have been identified in EVs associated with breast cancer." (PMID 40214422, 2025). "Meanwhile, as a potential inhibitor of RhoA, EGCG may also inhibit the recruitment and persistent education of CAFs in breast cancer by blocking the RhoA/Rho-associated kinase (ROCK) signaling pathway, thus suppressing the invasion of tumor cells." (PMID 38348027, 2024). "Breast cancer samples with phosphorylated RhoA (P-RhoA) were associated with poorer prognosis." (PMID 31339860, 2019). "Moreover, RhoA downregulation is associated with increased breast cancer cell migration and invasion." (PMID 30166526, 2018). "Our data demonstrate that NRF2 binds the ERR1 promoter region as a silencer and inhibits the expression of ERR1, which further stabilizes RhoA protein levels, leading to cytoskeletal changes that underlie cell proliferation and metastasis of breast cancer cells." (PMID 27713154, 2016). "Our results showed that P4 stimulated the cSrc/AKT signaling pathway to active RSK1, which in turn induced p27 phosphorylation at T198, subsequently increasing formation of the p27-RhoA complex and causing membrane translocation of RhoA, and finally enhanced migration in breast cancer cells." (PMID 27510838, 2016). "Therefore, we investigated whether reduced expression of RhoA contributes to the inhibition of breast cancer cell proliferation and metastasis by NRF2 deficiency." (PMID 27713154, 2016). "Clinically, RHOA lactylation levels are significantly elevated in breast cancer tissues compared to adjacent normal tissues." (PMID 41291745, 2025). "In breast cancer cells, doxorubicin enhances migration and invasion by activating the RhoA/MLC pathway." (PMID 40650042, 2025). "Overexpression of MCAM in noninvasive epithelial breast cancer cells induced migration and invasiveness associated with upregulation of EMT markers, through the RhoA pathway mediated by Slug." (PMID 41388158, 2025). "According to recent research, GPR116, a member of the mainly unidentified aGPCR family, activates the Gαq‐RhoA‐Rac1 pathway, contributing to the invasion and migration of breast cancer cells." (PMID 40969301, 2025). "NRF2 deletion hinders the proliferation and metastasis of breast cancer cells by downregulating the cytoskeleton-binding GTPase RhoA while restoring RhoA counteracted growth and metastasis suppression in vitro." (PMID 40507333, 2025). "We further analyzed the effects of RHOA lactylation and tumor-related mutations on the downstream signaling pathways of HEK293T and breast cancer cell lines." (PMID 41291745, 2025). "Our results for transcriptome sequencing prompted us to focus on the RhoA gene, for which a role has highlighted in tumor cell invasion and metastasis in malignancies such as breast cancer, nasopharyngeal carcinoma, and NSCLC." (PMID 38528546, 2024). "Another important oncogenic miRNA, miRNA-155, is frequently overexpressed in invasive breast cancer tissues and is directly targeted to RhoA and contributes to breast cancer metastasis." (PMID 38540304, 2024).
breast carcinoma (continued). "Upon EGF stimulation, RhoGDI1 phosphorylated at Ser174 binds to 14-3-3, promoting the dissociation of RhoA, Rac1 and Cdc42, which leads to their activation and results in cancer cell invasion and breast cancer metastasis." (PMID 39768163, 2024). "(2014) reported that miR‐182 significantly upregulates Ras homolog family member A (Rho A), which induces metastasis in breast cancer." (PMID 39617640, 2024). "Protein phosphatase 1B (PPM1B) dephosphorylates RhoGDI1 at Ser174, reduces RhoGDI1 interaction with 14-3-3, thereby inhibiting signaling of RhoA, Rac1, and Cdc42 in breast cancer cell migration." (PMID 39768163, 2024). "MDA-MB-231 breast cancer cells were transfected with Rac1, Cdc42, or RhoA biosensors and treated with P18 at a concentration of 25 μg/mL for 3 h." (PMID 38927935, 2024). "ROCK isoforms differentially regulate the RhoA/ROCK1/p-MLC and RhoA/ROCK2/p-cofilin pathways in a coordinated fashion to modulate breast cancer cell motility in a substrate stiffness-dependent manner through integrin β1-activated FAK signaling." (PMID 37916166, 2023). "Plexin-B1–mediated activation of RhoA/C is a key pathway promoting metastasis in ErbB2-mouse models of breast cancer." (PMID 36936664, 2023). "In breast cancer cells, mechanical compression activates Piezo1 and RhoA/Src/FAK/ERK signaling, which subsequently enhance tumor cell invasion, matrix degradation, and invadopodia formation." (PMID 37864030, 2023). "ECM stiffness activates Piezo2-mediated calcium influx in breast cancer cells preferentially metastasizing to the brain, which maintains the activation of RhoA, the orientation of stress fibers, and focal adhesions." (PMID 37864030, 2023). "Nonetheless, ROR-positive EVs increased migration and invasion of breast cancer cells, even after chemically inhibiting EV uptake, in dependence of RhoA downstream signaling." (PMID 37430307, 2023). "RhoA protein is highly expressed in gastric cancer, breast cancer, colon cancer, pancreatic cancer, lung cancer, and other cancers." (PMID 37446748, 2023). "In breast cancer cells, intratumoral hypoxia promotes the transcription of Rho family members RHOA and Rho-kinase 1 (ROCK1), and enhances the stress fiber formation, matrix contraction, and cell motility." (PMID 37864030, 2023). "It is well known that GPCR plays a related role through intracellular G protein, and it has reported that GPR116 receptor regulates RhoA and Rac1 to affect breast cancer metastasis through Gαq." (PMID 36895027, 2023). "Other researchers have found that inhibition of Cdc42 was responsible for the suppression of invasion ability in lung cancer, while the reduced RhoA had an anti-metastatic function on breast cancer." (PMID 36969843, 2023). "In this sense, Piezo channels, functionally expressed in malignant breast cancer cell lines, mediate Ca2+-influx to activate RhoA by a calpain-dependent mechanism regulating the formation and orientation of FAs." (PMID 37795261, 2023). "RhoA has also been shown to regulate breast cancer metastasis as an upstream signaling factor of Ezrin, where increasing RhoA phosphorylation resulted in enhanced Ezrin expression." (PMID 37371090, 2023). "We found that upregulated Rho GTPases RAC1, CDC42, and RHOA participated in the TGF-beta signaling pathway in the breast cancer MCF-7 cell line treated with DOX." (PMID 37511111, 2023). "Using Rho inhibitor ZOL and LIMK inhibitor BMS3, our data further confirmed that FMNL2 suppressed breast cancer cell migration and invasion by inhibiting RhoA/LIMK/Cofilin pathway through a reduction of cytoplasmic p27." (PMID 35379791, 2022). "Previous studies have shown that the decrease of RhoA protein plays a crucial role in the process of TGF-β-Par6 mediated EMT in breast cancer cells." (PMID 35379775, 2022).